EGF (epidermal growth factor)
Diseases named in the same sentence as EGF in open-access papers (continued):
Sharing a sentence is not in itself a finding about the gene and the disease.
synovitis (2 papers, 2005 to 2020). Inflammation of a synovial membrane. "Early RA synovial fluid was characterized by significantly elevated levels of T cell related cytokines (IL-2, IL-4, IL-13 and IL-17) and stromal cell and macrophage related cytokines (EGF, bFGF, IL-1 and IL-15) when compared with synovial fluid from patients with other early synovitis." (PMID 15987480, 2005). "The levels of plasma epidermal growth factor (EGF), colony stimulating factor 2 (CSF2), interleukin 4/13 (IL4/13), fibroblast growth factor 2 (FGF2) and MIP-1 α were significantly lower in patients with a joint bleeding compared to patients without a bleeding or synovitis." (PMID 33023246, 2020).
thyroid tumor (2 papers, 2005 to 2014). A benign or malignant neoplasm affecting the thyroid gland. "Moreover, in those patients whose thyroid tumours bound more EGF, the prognosis was reported to be poor." (PMID 15785737, 2005).
Traboulsi syndrome (2 papers, 2021 to 2024). "In 2014, Traboulsi syndrome was found to be linked to ASPH, an enzyme that hydroxylates asparagine‐ and aspartate‐residues on epidermal growth factor (EGF) domains of proteins." (PMID 33217155, 2021).
vulva carcinoma (2 papers, 2012 to 2025). A primary or metastatic malignant neoplasm involving the vulva. "The well-established vulvar carcinoma-derived A431 cell line was chosen for the experiments since it has served to characterize the keratin cytoskeleton and EGF signaling." (PMID 40564938, 2025). "In some EGFR over-expressing cell lines such as vulva carcinoma A431 cells, EGF at pM range stimulates cell proliferation while EGF at nM range induces growth inhibition, terminal differentiation and apoptosis." (PMID 22927910, 2012).
xerostomia (2 papers, 2023 to 2025). Dryness of the mouth resulting from reduced salivary secretion. "There is some limited effect on the use of a traditional Chinese medicine (Chining decoction, CHIN) when compared to a recombinant human epidermal growth factor spray in terms of acute xerostomia (VAS assessed at 7 weeks)." (PMID 39792256, 2025).
acromegaly (1 paper, 2022). Acromegaly is an acquired disorder related to excessive production of growth hormone (GH) and characterized by progressive somatic disfigurement (mainly involving the face and extremities) and systemic manifestations. "Although EGFR and EGF are abundantly expressed in somatotroph adenomas, trials evaluating TKI in treatment of aggressive acromegaly are lacking." (PMID 36545335, 2022).
acute coronary syndrome (1 paper, 2021). Signs and symptoms related to acute ischemia of the myocardium secondary to coronary artery disease. "In another study, patients in the acute phase of TTS had higher concentrations of interleukins 2, 4, 10, TNF-α, IFN-γ, and EGF, but lower levels of interleukin 6 compared to individuals with acute coronary syndrome." (PMID 34738019, 2021).
acute GVHD (1 paper, 2022). "In addition to MSCs, another example is the use of urinary-derived human chorionic gonadotropin/epidermal growth factor (uhCG/EGF) for the treatment of severe acute GVHD." (PMID 36189324, 2022).
acute myeloid leukemia (1 paper, 2016). Acute myeloid leukemia (AML) is a group of neoplasms arising from precursor cells committed to the myeloid cell-line differentiation. "In acute myeloid leukemia ELOVL6 appears to be activated by a novel chromosome rearrangement causing the activation of both EGF and ELOVL6." (PMID 26862848, 2016).
acute tubular necrosis (1 paper, 2018). "The similarities in the TIC analysis of EGF and DGF patients were further supported by the absence of differences in TTP and RT between early acute tubular necrosis (0.21 months) and stable patients (8.31 months)." (PMID 30537946, 2018).
adamantinoma (1 paper, 2016). A low grade malignant neoplasm arising from the long bones. "During progression of adamantinoma, the epithelial cells acquire expression of FGF-2, EGF, and EGFR, accompanied by a higher proliferative activity." (PMID 27630780, 2016).
aggressive periodontitis (1 paper, 2020). "Therefore, this study aims to investigate the association of the EGF rs2237051 variant and serum EGF levels in Chinese patients with generalized aggressive periodontitis (GAgP)." (PMID 32477838, 2020).
amyloid (1 paper, 2024). "Upregulation of the EGFR ligand, epidermal growth factor (EGF), reduces amyloid-related deficits without affecting levels of Aβ itself." (PMID 38167174, 2024).
anaplastic cancer (1 paper, 2005). "We thought that there might be a number of activated growth-stimulating pathways, other than the EGF–EGFR pathway, which must contribute to the growth of anaplastic cancer cells in conditions with FBS containing many growth factors." (PMID 15785737, 2005).
anemia (1 paper, 2021). A reduction in the number of red blood cells, the amount of hemoglobin, and/or the volume of packed red blood cells. "Hypoxia caused by anemia overexpresses hypoxia-inducible factor-1 (HIF-1), thereby inducing vascular endothelial growth factor, glucose transporter, epidermal growth factor, and glycolytic enzyme to promote tumor metabolism." (PMID 33506035, 2021).
angiomyolipoma (1 paper, 2015). A neoplasm with perivascular epithelioid cell differentiation often associated with tuberous sclerosis. "We previously demonstrated that tuberin-null cells, isolated either from angiomyolipoma or chylothorax of TSC and LAM patients, depend on EGF for survival and proliferation and this dependency is related to tuberin absence." (PMID 25699271, 2015).
aplastic anemia (1 paper, 2016). Anemia resulting from bone marrow failure (aplastic or hypoplastic bone marrow). "Epidermal growth factor (EGF) and CXCL5 were then lower in AA as well as MDS compared to controls, whereas only CCL2 was lower in aplastic anemia when compared to MDS." (PMID 27399678, 2016).
arbovirus infection (1 paper, 2021). A viral infection that is transmitted by an arthropod. "Soluble serum (IL-22, RANTES, Eotaxin) and CSF (IL-8, EGF, IL-3) mediators may discriminate putative risks for neurological complications following arbovirus infections." (PMID 33776990, 2021). "Besides EGF, IL-3 may also exert a protective role against brain damage in arbovirus infection, since IL-3 CSF levels were more than 25-folds higher than in serum, and few weak correlations were observed with other CSF molecules." (PMID 33776990, 2021).
Arrhythmia (1 paper, 2022). Any cardiac rhythm other than the normal sinus rhythm.
arterial disease (1 paper, 2022). "Concomitant arterial disease in mixed venous-arterial ulcers did not influence the levels of EGF, FGF-2, IL-1α, IL-1β, IL-6, PDGF, TGF-β1 and TNF-α in one study." (PMID 35742965, 2022).
autosomal dominant deafness (1 paper, 2021). "DFNA44, an autosomal dominant deafness, is tightly associated with the effector of EGF-mediated cell signaling." (PMID 34760891, 2021).
bartonellosis (1 paper, 2020). An infectious disease produced by bacteria of the genus Bartonella. "Moreover, the authors suggested that EGF could be involved in the pathological angiogenesis (i.e., verruga peruana) that is commonly observed in the chronic phase of human bartonellosis." (PMID 32302357, 2020). "There are several reports on the molecular basis of hyperproliferation of human VECs in response to a Bartonella infection, but the effectors involved are not uniform between species and a demonstrated role for EGF has not been reported, to date." (PMID 32302357, 2020).
benign ovarian tumors (1 paper, 2024). "Data suggest that benign ovarian tumors secret growth factors such as epidermal growth factor (EGF), transforming growth factor (TGF), and vascular endothelial growth factor (VEGF) whose receptors are often overexpressed in solid neoplastic tumors." (PMID 39507201, 2024).
bile reflux (1 paper, 2024). "Nevertheless, they proposed mechanisms for the effect of UDCA on bile reflux, noting that EGF plays an important role in maintaining mucosal integrity." (PMID 39422533, 2024).
bone tumor (1 paper, 2025). "Growth factors such as epidermal growth factor (EGF), B-27 minus vitamin A, fibroblast growth factor, and insulin-like growth factor are incorporated to promote the proliferation of bone tumor cells." (PMID 40271075, 2025).
bronchiolo-alveolar adenocarcinomas (1 paper, 2001). "Our results demonstrate that c- myc and EGF are directly involved and cooperate with one another during formation of bronchiolo-alveolar adenocarcinomas in the lung." (PMID 11259097, 2001).
Burkitt lymphoma (1 paper, 2022). A rare form of malignant mature B-cell non-Hodgkin lymphoma. "EGF application is able to enhance VEGF-A production and to induce PI3K-dependent positive feedback on AKT and ERK via VEGFR2 in hematological malignancies (human monocytic leukemia THP1 cell line and Burkitt’s lymphoma Raji cell line." (PMID 35252204, 2022).
burn (1 paper, 2020). A traumatic injury involving interruption of tissue cohesiveness that results from exposure to caustic chemicals, extreme heat, extreme cold or excessive radiation. "In this study, we have successfully prepared AM grafted with heparin, which can adsorb quickly, and sustained release EGF for treatment of ocular chemical burns." (PMID 33330430, 2020).
Cerebral Autosomal Dominant Arteriopathy with Subcortical Infarcts and Leukoencephalopathy (1 paper, 2021). "CADASIL (Cerebral Autosomal Dominant Arteriopathy with Subcortical Infarcts and Leukoencephalopathy) is a small vessel disease caused by mutations in NOTCH3 that lead to an odd number of cysteines in the epidermal growth factor (EGF)-like repeat domain, causing protein misfolding and aggregation." (PMID 34298974, 2021).
cervicitis (1 paper, 2021). An acute or chronic inflammatory process that affects the cervix. "The levels of EGF and iNOS in cervical tissue of rats also increased in different degrees, while the level of COX-2 decreased significantly (P<0.01), which significantly improved the pathological degree of vulvar inflammation in rats with cervicitis." (PMID 34852132, 2021).
chronic bronchitis (1 paper, 2018). A type of chronic obstructive pulmonary disease characterized by chronic inflammation in the bronchial tree that results in edema, mucus production, obstruction, and reduced airflow to and from the lung alveoli. "The epidermal growth factor (EGF) is a potent stimulant of human airway smooth muscle proliferation and an increase in its expression has been reported in the patients with chronic bronchitis." (PMID 29145138, 2018).
chronic hepatitis (1 paper, 2017). An active inflammatory process affecting the liver for more than six months. "Taken together, in the gene expression profile analysis, TCR- and chemokine-mediated pathways were enhanced in the process of chronic hepatitis, and, subsequently, EGF- and VEGF-mediated pathways were induced in the development of HCC." (PMID 28968425, 2017). "In a gene expression profile analysis of liver samples, the chemokine- and T cell receptor (TCR)-mediated pathways were enhanced during chronic hepatitis, and the EGF- and VEGF-mediated pathways were induced in HCC." (PMID 28968425, 2017).
chronic interstitial cystitis (1 paper, 2025). A condition with recurring discomfort or pain in the URINARY BLADDER and the surrounding pelvic region without an identifiable disease. "EGF, recognized for its urothelial regulatory role, is also increased in the urine of patients with chronic interstitial cystitis (IC)." (PMID 41035863, 2025).
chronic lung disease (1 paper, 2022). According to the definitions of the American and British Thoracic Societies, including pulmonary functional tests, X-rays, and CT scans for items such as fibrosis, bronchiectasis, bullae, emphysema, nodular or lymphomatous abnormalities. "Currie also indicated that epidermal growth factor in BAL may predispose chronic lung disease in premature infants." (PMID 35328399, 2022). "Furthermore, EGF significance in neonatal respiratory morbidities, for example, RDS, chronic lung disease, pulmonary hypoplasia, congenital diaphragmatic hernia, has been reported in animal and human research." (PMID 35328399, 2022).
chronic thromboembolic pulmonary hypertension (1 paper, 2022). Chronic thromboembolic pulmonary hypertension (CTEPH) is characterized by the persistence of thromboemboli in the form of organized tissue obstructing the pulmonary arteries. "We therefore quantified S100A4, EGF, and EGFR in patients suffering from chronic thromboembolic pulmonary hypertension (CTEPH) and idiopathic pulmonary arterial hypertension (iPAH)." (PMID 35053115, 2022).
Coffin-Lowry syndrome (1 paper, 2024). A rare X-linked syndromic intellectual disability characterized by global development delay, postnatal growth retardation leading to short stature, facial dysmorphism, short hands with tapering fingers and progressive skeletal abnormalities including kyphoscoliosis and pectus carinatum/excavatum. "Cells obtained from Coffin-Lowry syndrome (CLS) patients, caused by the deletion, nonsense, and missense mutations of RSK2, show defects in EGF-induced histone H3 phosphorylation, and introduction of RSK2-wt into CLS patient cells restores p-H3-S10 protein levels." (PMID 39424777, 2024).
complication (1 paper, 2020). Any disease or disorder that occurs during the course of, or because of, another disease, treatment, or procedure. "The down-regulation of pro-epidermal growth factor (EGF) may indicate the presence of the virus in the kidney and its malfunction based on the fact that the level of EGF is low in the urine of patients with kidney complications." (PMID 33244380, 2020).
congenital heart defects (1 paper, 2023). "Novel approaches, such as coating PTFE shunts with agents specifically suppressing pathways around EGF/EGFR and TIMP-1/MMP-9, might significantly reduce neointimal hyperplasia in SP shunts and therefore improve the outcome of children with complex and congenital heart defects." (PMID 36867212, 2023).
Corneal opacity (1 paper, 2022). A reduction of corneal clarity. "Together, these results support that bleogen pB1 and EGF share, in part, similar pathways to regulate immune response signaling and the TGF-β-extracellular matrix, which could be the underlying reasons for their potential benefits in reducing corneal opacity during corneal healing." (PMID 36052138, 2022).
coronary stenosis (1 paper, 2024). Narrowing of the coronary artery lumen diameter. "In addition, urinary Osteopontin was positively associated with coronary stenosis defined by CCTA, whereas EGF was inversely associated with coronary calcification defined by CACS in the fully adjusted model." (PMID 39587192, 2024).
corticotrope adenomas (1 paper, 2022). "Notably, CABLES1 is regulated by Akt, which is part of the EGFR signaling pathway, linking EGF and cell cycle regulation and potentially giving CABLES1 a pivotal role in the pathophysiology of corticotrope adenomas." (PMID 35743266, 2022).
craniosynostosis (1 paper, 2007). Craniosynostosis is defined as the premature fusion of one or more cranial sutures leading to secondary distortion of skull shape resulting in skull deformities with a variable presentation. "We identified differentially expressed genes in pathways that have been a major focus of study in craniosynostosis, including FGF, TGFβ and EGF signalling pathways." (PMID 18076769, 2007).
dacryoadenitis (1 paper, 2012). Inflammation and enlargement of the lacrimal gland. "Because the decrease in tear EGF concentration was accompanied by worsening dacryoadenitis and LG destruction, we correlated EGF levels with the factors that also increased with aging (that is, M3R autoantibodies and T-cell infiltration)." (PMID 23116218, 2012).
demyelinating CNS diseases (1 paper, 2022). "Particular attention is also given to the effects of EGF on NSCs, because this has aroused interest in the potential therapeutic use of EGF in some demyelinating CNS diseases." (PMID 33151415, 2022).
diabetic angiopathies (1 paper, 2022). "The EGFR family of RTKs have been found to be involved in multisystemic diabetic angiopathies, even though EGF has been proposed as a biomarker for DR." (PMID 36291965, 2022).
ductal adenocarcinoma (1 paper, 2011). "TGF-α expression was significantly higher in the ductal adenocarcinoma cells than in CAF (P=0.005), and EGF was equally expressed by both stroma and epithelial cancer cells." (PMID 21792199, 2011).
edema (1 paper, 2012). An abnormal accumulation of fluid beneath the skin, or in one or more cavities of the body. "The results demonstrated that EGF promotes the restoration of the lung vessels to repair lung, reduces pulmonary edema and improves the reversal of ALI." (PMID 23170113, 2012).
embryonal carcinoma (1 paper, 2022). A non-seminomatous malignant germ cell tumor characterized by the presence of large germ cells with abundant cytoplasm resembling epithelial cells, geographic necrosis, high mitotic activity, and pseudoglandular and pseudopapillary structures formation. "Before addressing this possibility, we first examined the involvement of EGF-dependent signaling in the ability of embryonal carcinoma P19 cells to undergo neural differentiation." (PMID 36206843, 2022).
endometrioid ovarian carcinoma (1 paper, 2020). "Studies on the impact of EGF on EMT in a model of endometrioid ovarian carcinoma revealed that EGF induction activated AKT and reduced levels of expressed PTEN, but did not increase cell proliferation." (PMID 31947591, 2020).
enteritis (1 paper, 2022). Inflammation of the small intestine. "To evaluate the therapeutic effect of CA-derived endothelial EGF on radiation-induced enteritis, we administered the CM of IR + CA HUVECs to an irradiated mouse model." (PMID 36010621, 2022). "Our findings also demonstrate that endothelial-derived EGF by CA treatment improved the epithelial barrier damage on radiation-induced enteritis." (PMID 36010621, 2022). "Collectively, the results indicated that CA recovered radiation-induced epithelial damage by regulating endothelial-derived EGF and that the interaction of epithelial-endothelial is a novel therapeutic target that can be used to alleviate radiation-induced enteritis." (PMID 36010621, 2022).
epidermolysis bullosa (1 paper, 2013). Epidermolysis bullosa (EB) is a group of genetic skin diseases that cause the skin to blister very easily. "It is unclear at present whether EGF-targeted treatment may be beneficial in certain Epidermolysis bullosa patients." (PMID 23391100, 2013).
epithelioid sarcoma (1 paper, 2021). An aggressive malignant neoplasm of uncertain differentiation, characterized by the presence of epithelioid cells forming nodular patterns. "But in contrast to epithelioid sarcoma, induction of SNAIL by panobinostat in A204 cells was further enhanced when stimulated with EGF." (PMID 34281526, 2021). "EGF clearly opposed this effect, relating EGFR signaling to epithelioid sarcoma dedifferentiation." (PMID 34281526, 2021).
essential thrombocythemia (1 paper, 2020). A chronic myeloproliferative neoplasm that involves primarily the megakaryocytic lineage. "Here we present a large-scale study of serum cytokine profiles in more than 400 MPN patients and identify an essential thrombocythemia (ET)-specific inflammatory cytokine signature consisting of Eotaxin, GRO-α, and EGF." (PMID 32647796, 2020).